BMS1P20 (BMS1 pseudogene 20)
Gene: Transcribed unprocessed pseudogene on chromosome 22 (22,303,224 to 22,310,401, forward strand). Ensembl gene ENSG00000272779.
Diseases named in the same sentence as BMS1P20 in open-access papers:
BMS1P20 is named in the same sentence as 4 diseases in open-access papers, as found by Europe PMC text mining. Sharing a sentence is not in itself a finding about the gene and the disease. The quoted sentences say what the papers report.
hepatocellular carcinoma (1 paper, 2017). A malignant tumor that arises from hepatocytes. "Taking hepatocellular carcinoma (LIHC) as a case study, we predicted four candidate lncRNA genes, RHPN1-AS1, AC007389.1, LINC01116 and BMS1P20 that may serve as novel disease risk factors for disease diagnosis and prognosis." (PMID 29383105, 2017).
lung adenocarcinoma (1 paper, 2022). A carcinoma that arises from the lung and is characterized by the presence of malignant glandular epithelial cells. "Previous studies have shown that BMS1P20 is positively corelated to cancer patients’ overall survival especially lung adenocarcinoma." (PMID 35484552, 2022).
metabolic syndrome (1 paper, 2022). A cluster of metabolic risk factors for CARDIOVASCULAR DISEASES and TYPE 2 DIABETES MELLITUS. "We have found rs403517 and rs405570 in BMS1P20 is related to DM, and we believe our study is the first to report BMS1P20 lnc-RNA is related to metabolic syndrome." (PMID 35484552, 2022).
cancer (2 papers, 2017 to 2022). A tumor composed of atypical neoplastic, often pleomorphic cells that invade other tissues. "Consequently, four survival-related lncRNAs including ENSG00 000254389 (RHPN1-AS1), ENSG00000204929 (AC0743 91.1), ENSG00000163364 (LINC01116) and ENSG000 00236850 (BMS1P20) were found and some of them were significantly correlated with the pathogenesis, development and metastasis of cancers." (PMID 29383105, 2017).